RB1 (RB transcriptional corepressor 1)
Diseases named in the same sentence as RB1 in open-access papers (continued):
Sharing a sentence is not in itself a finding about the gene and the disease.
retinoblastoma (continued). "Besides causing retinoblastoma, mutations and inactivation of RB1 occur in osteosarcoma, lung, bladder, esophageal, and breast malignancies." (PMID 35299734, 2022). "For instance, in retinoblastoma, one recessive allele of the RB1 gene may be inherited or result from an early somatic mutation, and the loss of chromosome 13 carrying the RB1 gene is a frequent second genetic change that leads to LOH of RB1." (PMID 35287703, 2022). "Hereditary Rb arises due to bilateral genetic mutations in RB1 gene located in chromosome 13." (PMID 35359459, 2022). "As predicted by the “two-hit hypothesis,” hereditary retinoblastoma patients inherit a mutationally inactivated RB1 allele from one parent while the remaining allele is inactivated somatically." (PMID 35368709, 2022). "In this form, both wild-type alleles of RB1 gene are inactivated in the tumor tissue, leading to a single unifocal tumor, whereas children with heritable retinoblastoma have a constitutional pathogenic variant in RB1 and thus only require a mutation of the second allele to initiate cancer." (PMID 36497295, 2022). "The plasma cfcDNA can also detect somatic RB1 mutations in patients with unilateral retinoblastoma." (PMID 35269741, 2022). "The RB1 gene is the first family of oncogenes discovered in humans and is an oncogene that regulates the cell cycle, which is closely linked to the development of retinoblastoma." (PMID 35911143, 2022). "Mutational loss of RB1 function is the primary cause of the pediatric cancer retinoblastoma." (PMID 35368709, 2022). "Indeed, loss of RB1 results in aneuploidy in both retinoblastoma patient-derived fibroblasts and mouse models." (PMID 34983823, 2022). "It is unknown whether BRB73, carrier of the RB1 donor splice site variant, had retinoblastoma as a child." (PMID 35039564, 2022). "They account for 40% of pineal parenchymal tumors, they tend to be more common in females and they can be associated with retinoblastomas in trilateral retinoblastoma (concomitant presentation of an intraocular retinoblastoma with a pineoblastoma due to RB1 gene mutation)." (PMID 35455578, 2022). "Considering the genetic RB1 pathogenic variations in our population, we emphasize the 3 cases of unilateral hereditable retinoblastoma, 2 of which had a positive family history of retinoblastoma also presenting unilaterally in the affected progenitor." (PMID 35288594, 2022). "In contrast to humans, loss of Rb1 is insufficient to cause murine retinoblastoma." (PMID 35368709, 2022). "Fifteen children were included in the hereditary retinoblastoma group, from which 12 presented with bilateral retinoblastoma and 3 were unilateral but had a positive genetic test for a RB1 pathogenic variant (2 of these had known family history of retinoblastoma)." (PMID 35288594, 2022). "Using a multi-omics approach, retinoblastoma was classified into two subtypes: Subtype 1 retinoblastoma are associated with younger age at diagnosis, heritable disease, low rate of genetic aberrations other than RB1 and a higher grade of photoreceptor differentiation." (PMID 35565295, 2022). "Approximately 40% of cases of retinoblastoma occur bilaterally, a finding which is indicative of heritable autosomal dominant susceptibility, attributable to a germline loss‐of‐function mutation in the RB1 gene (OMIM: 180200)." (PMID 35014072, 2022). "In contrast to the typical retinoblastoma sequence, in which all cells of the body harbor a heterozygous germline RB1 deletion and where biallelic RB1 loss triggers oncogenesis, most tumor types characterized by RB1 deletion acquire this by somatic means." (PMID 33802620, 2021). "Finally, retinoblastoma patients can have non-RB1 germline mutations in other cancer-associated genes." (PMID 33466343, 2021). "In the future, we hope to discover how these alternate non-RB1 germline mutations may influence the primary ocular retinoblastoma, the metastatic potential or additional primary malignancies." (PMID 33466343, 2021).
retinoblastoma (continued). "The probands with retinoblastoma inherited the RB1 mutation from their fathers who were asymptomatic carriers or had a milder disease form (late-onset and/or unilateral retinoblastoma) in 11 families and from the mothers who were asymptomatic carriers in five families." (PMID 34680218, 2021). "However, the cell type in which RB1 suppresses retinoblastoma and the circuitry that underlies the need for retinoblastoma are undefined." (PMID 34815392, 2021). "Finally, patients with somatic mutational mosaicism, which is present in a considerable fraction of patients with isolated retinoblastoma, are known to develop fewer tumor foci compared to patients heterozygous for a pathogenic RB1 variant." (PMID 33807189, 2021). "Although Knudson’s “two-hits hypothesis” suggests that a loss of function of both RB1 alleles is required to initiate retinoblastoma, using standard clinical screening techniques, in 3–4% of tumours, only one RB1 mutation can be identified." (PMID 33670346, 2021). "In addition to RB1 loss, gain of chromosome 6p has been found to be present in most patients with retinoblastoma." (PMID 36246172, 2021). "An effect of the parental origin of the RB1 mutation is currently thought to provide a molecular mechanism that underlies the variation in phenotypic expression of the same mutation in different members of a family with hereditary retinoblastoma." (PMID 34680218, 2021). "However, WGS allowed us to look at the full compendium of mutations in our cohort of retinoblastomas and suggests that driver mutations beyond RB1, MYCN BCOR and recurrent copy number changes on 1q, 2p, 6p, and 16q are rare." (PMID 33670346, 2021). "Loss of function in both copies of the RB1 gene is the causal mutation of retinoblastoma." (PMID 34639028, 2021). "Additionally, when compared to other cancer types, RB1 is subject to CN-LOH at much higher rates in retinoblastoma than in other cancers that also contain mutations in RB1 (p-value < 2.2 × 10−16, OR 44.4)." (PMID 33466343, 2021). "Retinoblastoma (RB) is a cancer in children, caused by loss of function of RB1 gene." (PMID 34680394, 2021). "The RB1 gene is the first tumor suppressor gene found as the cause of retinoblastoma." (PMID 34671549, 2021). "Furthermore, retinoblastoma patients can have non-RB1 germline mutations in other cancer-associated genes." (PMID 33466343, 2021). "In addition to advanced unilateral disease, IVC can also be used to manage bilateral retinoblastoma with a germline RB1 mutation." (PMID 34195690, 2021). "Four family cohorts (n = 9) consented to the protocol, including two families where the parent was previously unknown to carry the RB1 mutation until the children were diagnosed with bilateral or trilateral retinoblastoma." (PMID 34315877, 2021). "In 1971, the “two-hit” mutation hypothesis was proposed to explain the cause of retinoblastoma, and the RB1 gene was identified 16 years later." (PMID 34639028, 2021). "The common driver event of retinoblastoma is loss of RB1 during retinal development." (PMID 33718380, 2021). "Three children had familial retinoblastoma with a proven RB1 mutation (23%)." (PMID 33924716, 2021). "Patients with a 13q deletion containing RB1 show a variable phenotype that, depending on the size and location of the deleted region, includes ID, growth retardation, craniofacial dysmorphisms, congenital malformations, and increased risk of retinoblastoma." (PMID 34573300, 2021). "Retinoblastoma modeling using GEMMs has proven challenging, as engineering of Rb1-deficient mice resulted in embryonic lethality and retina-specific depletion of Rb1 was required." (PMID 33718380, 2021). "Retinoblastoma is a heritable pediatric cancer driven by mutations in RB1." (PMID 34315877, 2021). "In addition to mutations, three patients exhibited MYCN amplification, in the presence of an RB1 mutation, which has been shown previously to be prevalent in retinoblastoma." (PMID 33466343, 2021).
retinoblastoma (continued). "The second most highest cited paper, also published in Nature in 2012, supposed that the epigenetic deregulation of key cancer pathways caused by RB1 loss may lead to the rapid development of retinoblastoma." (PMID 34095180, 2021). "Some families with hereditary retinoblastoma exhibit mild phenotype with low penetrance and variable expressivity, including complete absence of clinical signs of the disease in some carriers of the germline RB1 mutation." (PMID 34680218, 2021). "Retinoblastoma (RB) is initiated by mutations in the RB1 tumor suppressor gene." (PMID 33821340, 2021). "Previous studies have suggested that age of onset and incidence of SPM in individuals with heritable retinoblastoma are influenced by the type of pathogenic RB1 allele, and risk is highest in children with variants that are regularly associated with complete penetrance for retinoblastoma." (PMID 33807189, 2021). "Retinoblastoma is a malignant disease, most commonly caused by two mutations in the RB1 gene." (PMID 35087971, 2021). "By NGS and MLPA, RB1 mutations were found in 191 from 332 unrelated retinoblastoma patients." (PMID 34680218, 2021). "Unlike the penetration of the germline RB1 mutation in human retinoblastoma, mice cannot develop retinoblastoma with similar disruption of the Rb1 gene, even if pRb is completely inactivated, because pRb-related proteins p107 (RBL1) and p130 (RBL2) compensate for functional loss of pRb." (PMID 32824373, 2020). "Retinoblastoma is generally caused by a biallelic mutation of the RB1 gene." (PMID 32113195, 2020). "As treatment of retinoblastoma continues to improve ocular survival, fewer tissue samples will be available to determine the tumor's mutational profile, and an alternative method to determine the RB1 mutation status will be required." (PMID 32633890, 2020). "Retinoblastoma develops in response to the biallelic loss of RB1 gene." (PMID 32669100, 2020). "RB1 loss (RB1null) or MYCN amplification (MYCNamp) in fetal human retina causes retinoblastoma." (PMID 32123578, 2020). "Plasma cfDNA can detect somatic RB1 mutations in patients with unilateral retinoblastoma." (PMID 32633890, 2020). "Retinoblastoma (Rb) is a malignant tumor of the developing retina that affects children before the age of five years in association with inherited or early germline mutations of the RB1 gene." (PMID 33375764, 2020). "Over 99% of retinoblastomas are due to bi-allelic inactivation in the RB1 gene, caused by either two somatic mutations or an initial germline mutation followed by a subsequent somatic hit as described in Knudson’s two-hit hypothesis." (PMID 33143217, 2020). "We analyzed cfDNA collected from 10 patients with available tumor tissue to determine whether sufficient tumorderived cfDNA is shed in plasma from retinoblastoma tumors to enable noninvasive RB1 mutation detection." (PMID 32633890, 2020). "Retinoblastoma patients who are RB1 mutation carriers have been reported to have a higher chance of secondary cancers; although there is limited evidence that chemotherapeutic agents lead to secondary cancer in retinoblastoma patients." (PMID 33271982, 2020). "It’s the first report to describe RB1 mutations in Yunnan children with retinoblastoma." (PMID 33225895, 2020). "Furthermore, approximately half of survivors carry a constitutional RB1 mutation (heritable retinoblastoma), which confers an increased risk of second malignancies and potential to pass the disease causing allele to future offspring." (PMID 32770435, 2020). "Retinoblastoma (Rb) is a retinal tumor of infancy and childhood caused primarily by biallelic inactivation of the RB transcriptional corepressor 1 (RB1) tumor suppressor gene [Gene ID: 5925; Online Mendelian Inheritance in Man (OMIM) 614041] located on chromosome 13." (PMID 32218800, 2020). "In addition, the knowledge of a somatic RB1 mutation can eliminate anxiety concerning the risk of retinoblastoma for current and future family members." (PMID 32633890, 2020).
retinoblastoma (continued). "However, compared with other cancers including RB1-deficient malignancies, retinoblastoma exhibits minimal genomic instability because of unique cell type-specific circuitry." (PMID 32824373, 2020). "Heritable retinoblastoma is caused by a germline mutation in the RB1 gene." (PMID 33143217, 2020). "Using the Sanger sequencing methods, the FGFR4 p.Gly388Arg variant was bidirectionally sequenced in 49 patients with non-RB1 gene mutation in retinoblastoma patients and 13 healthy first-degree relatives and 146 individuals matched by sex and age in the control group." (PMID 33456465, 2020). "Development of retinoblastoma is associated with mutations of both alleles of the RB1 gene." (PMID 32047660, 2020). "NGS and RB1 custom array-comparative genomic hybridization (aCGH) methods were recently used on a cohort of RB patients to optimize diagnostic procedures and to identify genomic abnormalities in retinoblastoma." (PMID 31835688, 2019). "Retinoblastoma is the most common eye malignancy in childhood caused by mutations in the RB1 gene." (PMID 30745306, 2019). "The majority (85%) of RB1 pathogenic variants in retinoblastomas are within this locus." (PMID 31683923, 2019). "Bilateral hereditary retinoblastoma can also be due to a de novo germline mutation in RB1." (PMID 29533992, 2018). "Retinoblastoma tumors typically develop in infants and children during the process of retinal development when trophic factors are present to direct differentiation and block cell death caused by loss of RB1." (PMID 28445155, 2017). "While the rate of second malignancies in retinoblastoma survivors with low-penetrance or mosaic RB1 mutations is still unknown, it is presumed to be lower than those with germline null RB1 alleles." (PMID 28575107, 2017). "In this study, we used murine retinoblastoma models where we can monitor different levels of UHRF1 expression according to the extent of Rb1 inactivation which may be a physiological cause for high UHRF1 expression in retinoblastoma." (PMID 28467809, 2017). "Loss of the RB1 tumor suppressor gene is the primary driving mutation in human retinoblastoma." (PMID 28445155, 2017). "These experimental evidences demonstrate that Rb1 inactivation may be implicated in the high expression of UHRF1 in retinoblastoma through deregulated E2F proteins." (PMID 28467809, 2017). "Upon initial diagnosis of retinoblastoma, rapid identification of whether it is a germline RB1 mutation, sporadic RB1 mutation or a RB1+/+ MYCNA is necessary for correct treatment, as well as risk assessment for patents and their families." (PMID 29124525, 2017). "It is hypothesized that retinoblastoma tumors develop with so few other mutations besides RB1 itself owing to a unique cell-intrinsic signaling circuitry." (PMID 28445155, 2017). "A platform for initiation of retinoblastoma in a developing human retina in vitro would allow unique freedom to test various temporal settings for the mutagenic events e.g. loss of RB1 function on different levels or gain of a MYCN or OTX2 amplification at different steps in retinal development." (PMID 29124525, 2017). "Although mutations in RB1 are often considered a prerequisite for retinoblastoma initiation, further genomic changes may drive malignancy by activating oncogenes and inactivating tumor suppressor genes." (PMID 29124525, 2017). "Furthermore, survivors of a bilateral retinoblastoma with an inherited germline retinoblastoma have a slightly higher risk of secondary cancers compared with those with a de novo germline RB1 mutation." (PMID 29124525, 2017). "Interestingly, MYCN expressing retinoblastomas are larger than RB1-only mutated retinoblastomas of the equivalent age." (PMID 28358317, 2017).